FGF23 (fibroblast growth factor 23)
Diseases named in the same sentence as FGF23 in open-access papers (continued):
Sharing a sentence is not in itself a finding about the gene and the disease.
chronic kidney disease (continued). "In a model of chronic kidney disease, the 5/6 nephrectomized rat, we have repeatedly measured severely increased plasma levels of FGF23." (PMID 33233840, 2020). "Symptoms of SHPT are caused by altered bone metabolism, in which elevated PTH and FGF23 levels, low/normal calcemia, and low 1α,25-(OH)2D variably contribute to the bone alterations defining the chronic kidney disease-mineral bone disease (CKD-MBD)." (PMID 32751307, 2020). "Plasma FGF23 concentrations in humans and animals with chronic kidney disease are also correlated with serum phosphorus concentrations, and, in some studies, with plasma PTH concentrations." (PMID 33027890, 2020). "Subsequent research is expected to evaluate the role of Klotho and FGF-23 in left ventricular diastolic dysfunction and progression to heart failure in patients with chronic renal disease." (PMID 30934737, 2019). "Cardiovascular disease is the leading cause of mortality across all stages of chronic kidney disease (CKD), and common occurrences such as fibroblast growth factor 23 (FGF23) excess, chronic inflammation and iron deficiency have been shown as prominent risk factors." (PMID 31461904, 2019). "In patients with CKD, FGF23 concentrations increase with declining renal function and reach extremely high levels in end-stage renal disease." (PMID 31542779, 2019). "FGF23 seems to be a positive predictor for mortality or cardiovascular complications in chronic kidney disease, heart failure and sepsis." (PMID 32309615, 2019). "Patients with chronic kidney disease (CKD) are prone to developing cardiac hypertrophy and fibrosis, which is associated with increased fibroblast growth factor 23 (FGF23) serum levels." (PMID 31540546, 2019). "Emerging data from disease populations such as chronic kidney disease (CKD) patients suggest that iron deficiency stimulates the expression and concomitant cleavage of the osteocyte-derived, phosphate-regulating hormone fibroblast growth factor 23 (FGF23)." (PMID 31170159, 2019). "Abnormal serum concentrations of calcium and fibroblast growth factor 23 (FGF23) are two of a group of interrelated metabolic disturbances—collectively referred to as the chronic kidney disease-mineral bone disorder (CKD-MBD)—that are implicated in the high morbidity and mortality rates in CKD." (PMID 31615041, 2019). "Several studies showed that increased serum FGF23 during chronic kidney disease is a reliable prognostic marker." (PMID 32309615, 2019). "The plasma level of FGF23 correlates well with progression of chronic kidney disease (CKD) and is a very sensitive marker that is elevated even before onset of hyperphosphatemia or hyperparathyroidism." (PMID 30921339, 2019). "Moreover, serum FGF-23 was shown to be independently associated with LVH in chronic kidney disease (CKD)." (PMID 30462803, 2018). "We reported that the increased levels of FGF23 in chronic renal disease stimulate αKlotho/FGFR signal transduction, enhancing the growth and hormone secretion of the parathyroid glands." (PMID 29720668, 2018). "Ectopic renal FGF23 expression has been reported in animal models of chronic kidney disease and in mice with unilateral ureter obstruction." (PMID 30405444, 2018). "FGF23 plays a pivotal role in mineral metabolism and is consistently increased in patients with chronic kidney disease." (PMID 29856857, 2018). "Consistent with this, elevated FGF23 levels are associated with inflammatory markers as well as parathyroid hormone (PTH) in various disease states, including chronic kidney disease (CKD)." (PMID 29527594, 2018). "Based on the importance of diseases associated with gain of FGF23 function such as phosphate-wasting diseases and chronic kidney disease, a large body of literature has focused on the pathophysiological consequences of FGF23 excess." (PMID 29892265, 2018).
chronic kidney disease (continued). "Small studies in health and chronic kidney disease, have demonstrated marked intra- and inter-individual variability in measured FGF-23 levels, and variable degradation in serum as compared to plasma samples." (PMID 30428848, 2018). "Chronic kidney disease patients have reduced viable nephrons and elevated FGF-23 which impairs activation of 1α-hydroxylase and therefore leads to low serum levels of 25-hydroxy vitamin D and consequently calcitriol." (PMID 29607318, 2018). "Data from a Chronic Renal Insufficiency Cohort study show that the first alteration observed is elevated serum FGF23, followed be decreased serum 1,25D, elevated serum PTH, and eventually elevated serum phosphate." (PMID 30249044, 2018). "This study aimed to evaluate the effect on chronic kidney disease-mineral and bone disorder, FGF23, renal anemia, iron-related parameters, adverse events of sucroferric oxyhydroxide in hemodialysis patients." (PMID 29884226, 2018). "Increased blood levels of FGF-23 are described in patients with chronic renal disease and to be a predictor of the mortality in dialysis patients." (PMID 28792535, 2017). "We examined the effect of marine n-3 fatty acids eicosapentaenoic acid (EPA) and docosahexaenoic acid (DHA) and plant-derived alpha-linolenic acid (ALA) on plasma FGF23 levels in post-myocardial infarction patients with chronic kidney disease." (PMID 29137111, 2017). "FGF23 levels are increased in patients with chronic kidney disease (CKD), particularly those on dialysis, in response to increased phosphate levels, increased PTH levels, and intervention of vitamin D." (PMID 28475601, 2017). "Physiologically, elevations of FGF23 in chronic renal disease likely are due to decreased phosphate clearance as the number of functioning nephrons decrease." (PMID 28497083, 2017). "In cells and mice, it blocked ppGalNAc-T3-mediated glycan-masking of FGF23 thereby increasing its cleavage, a possible treatment of chronic kidney disease." (PMID 28362263, 2017). "Fibroblast growth factor 23 (FGF23) is a known biomarker for chronic kidney disease (CKD) and was recently shown to impair neutrophil arrest on endothelium and transendothelial migration." (PMID 28596573, 2017). "An inhibitor of ppGalNAc-T3 was identified and found to block breast cancer cell invasiveness as well as secretion of intact FGF23 promising new therapeutic approaches for cancer and chronic kidney disease, respectively." (PMID 28362263, 2017). "In some studies, it has been demonstrated that patients with end-stage renal disease have elevated FGF23 concentrations that correlate with serum phosphate concentrations." (PMID 28497083, 2017). "Fibroblast Growth Factor-23 has been shown to be significantly elevated in patients with chronic kidney disease as FGF-23 metabolism and clearance are modified, which subsequently improves following kidney transplantation." (PMID 27770793, 2016). "In conclusion: Plasma FGF23 concentration rises early in the course of chronic kidney disease, most probably to compensate the inability of the deteriorating kidneys to excrete an adequate amount of phosphate." (PMID 27941640, 2016). "The regulation of FGF23 secretion in patients with chronic kidney disease (CKD) is incompletely understood." (PMID 27495287, 2016). "In CKD (chronic kidney disease) patients, plasma FGF23 concentration raises as early as in stage 2, which is much earlier than when the significant changes of phosphatemia or serum PTH concentration occur." (PMID 27941640, 2016). "Consistent with its role in bone mineral regulation, which becomes disordered in patients with kidney disease, several studies demonstrated that FGF23 levels rise as kidney function declines, even among individuals with early chronic kidney disease (CKD)." (PMID 27176000, 2016). "It has been demonstrated that FGF23 is elevated in cats with chronic kidney disease, and increases with disease progression." (PMID 26870965, 2016).
chronic kidney disease (continued). "In patients undergoing hemodialysis, increased serum FGF23 levels were an independent risk of coronary artery disease (CAD) and mortality in patients with chronic kidney disease." (PMID 26459301, 2015). "Serum FGF23 levels are significantly increased in chronic kidney disease, indicating the important role of FGF23 in maintaining a neutral phosphate balance as the glomerular filtration rate decreases." (PMID 26483756, 2015). "In chronic kidney disease (CKD), elevated FGF23 levels are associated with worse outcomes." (PMID 26491212, 2015). "Higher FGF23 levels have been related to the development of cardiovascular disease (CVD) in chronic kidney disease patients." (PMID 26193703, 2015). "Fibroblast growth factor 23 is an excellent marker of disease severity and outcomes, particularly in chronic kidney disease." (PMID 26491212, 2015). "Among patients with end-stage renal disease, serum levels of FGF23 increase in response to elevated serum phosphorus." (PMID 25200959, 2014). "Expression and/or excretion of fibroblast growth factor-23 (FGF23) and its co-receptor Klotho are altered in patients with end-stage renal disease." (PMID 25200959, 2014). "Both 1,25(OH)2vitamin D, other 1α-hydroxylated vitamin D analogues and cholecalciferol in doses of 40000 IU per week increase the circulating levels of FGF23 in patients with chronic kidney disease." (PMID 25166750, 2014). "Chronic kidney disease (CKD) is regarded as a state of Klotho deficiency and FGF23 excess." (PMID 24695641, 2014). "Elevated serum FGF-23 levels prior to determination of iPTH levels in chronic kidney disease and higher FGF-23 levels in patients with refractory secondary hyperparathyroidism assert the importance of FGF23-Klotho axis." (PMID 25295189, 2014). "Among patients with end-stage renal disease, serum levels of FGF23 increase in response to elevated serum phosphorus, and those of α-Klotho decrease." (PMID 25200959, 2014). "Today, despite similar duration of disease, etiology, and demographic features, studies conducted in the patients with chronic kidney disease and dialysis patients are trying to explain the differences between the serum FGF-23 levels." (PMID 25295189, 2014). "The influence of cholecalciferol and active vitamin D metabolites on FGF23 has also been described in patients with chronic kidney disease." (PMID 25166750, 2014). "In the current study, we showed that serum UA was associated with LV hypertrophy independently of PTH levels and other possible confounders, including age, high blood pressure chronic kidney disease, and FGF23 level, in cardiac patients." (PMID 24340056, 2013). "Fibroblast growth factor-23 (FGF-23), a novel marker of bone disease in chronic kidney disease (CKD) has been shown to correlate with vascular calcifications." (PMID 23413976, 2013). "Considering that cardiovascular events are increased in patients with a low estimated glomerular filtration rate (eGFR), the possibility exists that increased FGF23 levels mediate an adverse cardiovascular outcome among patients with end-stage renal disease." (PMID 24039882, 2013). "Secondary hyperparathyroidism (sHPT) is a common manifestation in chronic kidney disease (CKD) despite markedly increased serum FGF23 concentrations." (PMID 24348262, 2013). "Several studies reported that high levels of FGF23 are related to left ventricular hypertrophy and progression of chronic kidney disease." (PMID 23705925, 2013). "The aim of this study is to examine the effect of IV ferric carboxymaltose(FCM) on phosphate metabolism and FGF23 levels in patients with chronic kidney disease(CKD)." (PMID 23902731, 2013). "In patients with chronic kidney disease, the serum level of the active form of vitamin D3 is decreased because of elevated blood concentration of fibroblast growth factor-23 (FGF-23) and related inflammatory cytokines." (PMID 24967240, 2013).
chronic kidney disease (continued). "Fibroblast growth factor-23 (FGF-23) is a phosphaturic hormone that increases in early chronic kidney disease (CKD) before abnormalities in serum calcium, phosphate, or parathyroid hormone (PTH) become apparent." (PMID 23413976, 2013). "In chronic kidney disease, FGF23 is one of the strongest predictors of mortality, and adverse cardiovascular outcomes." (PMID 22970174, 2012). "Fibroblast growth factor 23 (FGF23) has emerged as a risk factor for cardiovascular disease and mortality throughout all stages of chronic kidney disease (CKD), independent from established risk factors and markers of mineral homeostasis." (PMID 22530966, 2012). "Fibroblast growth factor-23 (FGF23) is a bone derived, phosphate regulating hormone which is often elevated in genetic hypophosphataemic disorders and in chronic kidney disease." (PMID 23098062, 2012). "The aim of the present prospective study was therefore to investigate FGF-23 levels in patients with end-stage renal disease before and after a successful renal transplantation and their probable association with markers of bone and mineral metabolism." (PMID 20107581, 2009). "We performed a prospective study to investigate FGF-23 levels in patients with end-stage renal disease before and after renal transplantation and their probable association with markers of bone and mineral metabolism." (PMID 20107581, 2009). "Serum FGF-23 concentrations are elevated in patients with chronic renal failure (CRF), and the increase in FGF-23 correlates with the decline in glomerular filtration rate." (PMID 18288501, 2008). "We discuss the role of FGF23 in bone mineralisation, phosphocalcium metabolism and energy homeostasis, as well as its involvement in inflammatory states, anaemia, cardiovascular disease, chronic kidney disease, cancer and nervous system function." (PMID 41833603, 2026). "Additionally, phosphate dysregulation is associated with elevated levels of fibroblast growth factor-23 (FGF23), closely linked to the progression of chronic kidney disease and cardiovascular disease." (PMID 40839579, 2025). "Chronic kidney disease (CKD) is associated with many disturbances in the homeostasis of calcium, phosphate, parathyroid hormone (PTH), calcitriol, fibroblast growth factor 23 (FGF23), and Klotho." (PMID 41303166, 2025). "Inhibitors of NaPis elicit phosphaturia and may reduce levels of PTH and FGF23 in chronic kidney disease (CKD) models." (PMID 40357590, 2025). "Higher FGF23 levels have also been linked with an increased cardiovascular risk in patients with diabetes, even without chronic kidney disease." (PMID 40237064, 2025). "In the PREVEND study, on a prospective population-based cohort, high FGF-23 levels were associated with an increased risk of new-onset chronic kidney disease and all-cause mortality, independent of established chronic kidney disease risk factors." (PMID 40136613, 2025). "When interpreting intact FGF23 concentrations, it is essential to consider factors that may affect interpretation, as patients with chronic kidney disease typically have repeatedly elevated FGF23 concentrations from the early stages onwards." (PMID 41008628, 2025). "The nature of secondary hyperparathyroidism (SHPT) is a compensatory response of the parathyroid glands to chronic pathological stimuli, with core triggers including chronic kidney disease (CKD)-related phosphorus retention, active vitamin D deficiency and fibroblast growth factor 23 (FGF23)." (PMID 41210508, 2025). "We evaluated whether baseline intact FGF-23 (iFGF-23) predicts kidney disease progression in the Indian Chronic Kidney Disease (ICKD) cohort." (PMID 41561945, 2025). "Studies have shown that in patients with chronic kidney disease, the active FGF23 signaling pathway may lead to impaired recruitment of neutrophils, thereby weakening the host defense ability." (PMID 40969364, 2025). "Persistent elevated FGF23 in chronic kidney disease has been reported to increase mortality." (PMID 40687705, 2025).
chronic kidney disease (continued). "Understanding the relationship between FGF23, iron homeostasis, and erythropoiesis may lead to novel therapies for anemia and FGF23 excess conditions, such as chronic kidney disease." (PMID 39857726, 2025). "In end-stage renal disease, FGF-23 levels may be up to 1,000 times higher than normal, which is consistent with previous research results." (PMID 40950978, 2025). "In addition, the elevation of FGF23, which is linked with vitamin D deficiency, is associated with the progression of CKD towards end-stage renal disease (ESRD), the occurrence of cardiovascular (CVS) events and increased mortality rates in patients with CKD." (PMID 38541146, 2024). "In chronic kidney disease (CKD), alterations in FGF23 cleavage mechanisms are also observed, although the underlying mechanisms are unknown." (PMID 38732094, 2024). "Moreover, significant research has been conducted on the role of Fibroblast Growth Factor 23 (FGF23) in the pathophysiologic axis of anemia and inflammation, especially in chronic kidney disease (CKD)." (PMID 39336155, 2024). "FGF-23 acts as a phosphaturic hormone, a circulating endocrine regulator of mineral metabolism, and a significant cardiac biomarker, and it is particularly noted for its role in chronic kidney disease (CKD) and HF." (PMID 39273041, 2024). "Despite promising therapeutic implications in targeting FGF23 signaling, further research is imperative to elucidate its precise mechanisms and potential therapeutic benefits, particularly in chronic kidney disease where elevated FGF23 levels contribute to adverse outcomes." (PMID 38732094, 2024). "Similarly, a study in the Japanese population with early-stage chronic kidney disease (CKD) reported an optimal cutoff point of 56.8 pg/mL for FGF-23 levels in predicting vertebral fractures." (PMID 39200293, 2024). "In the Predictors of Arrhythmic and Cardiovascular Risk in End Stage Renal Disease (PACE) cohort, primarily comprising incident hemodialysis patients of African American descent, elevated serum FGF-23 levels were associated with a higher prevalence of coronary artery calcification." (PMID 38402283, 2024). "Additionally, IL-6 elevates serum fibroblast growth factor 23 (FGF23) levels via sIL-6R, promoting the development of acute and chronic renal failure." (PMID 39749325, 2024). "Interestingly, FGF23, which binds to the FGF receptor-Klotho complex, exerts a significant inhibitory effect on Klotho transcription, explaining the observed reduction in Klotho levels in conditions such as chronic kidney disease that elevate FGF23 production." (PMID 40799848, 2024). "This multicenter observational study showed that patients with end-stage renal disease in chronic hemodialysis who presented high baseline plasma levels of FGF23 had a higher rate of SARS-CoV-2 infection and severe COVID-19, including hospitalizations and deaths." (PMID 36828412, 2023). "In healthy subjects FGF-23 is expressed at low levels in osteocytes, but is significantly increased in osteocytes in patients with hypophosphatemic rickets and in patients with chronic kidney disease." (PMID 36996072, 2023). "Fibroblast growth factor-23 (FGF-23) is used to monitor chronic kidney disease in humans." (PMID 37889764, 2023). "FGF23 is normally expressed at considerably low levels in osteocytes but its expression is considered to be increased in patients with hypophosphatemic rickets and in patients with chronic kidney disease." (PMID 36776964, 2023). "However, when present with other stimuli such as elevated phosphate in the context of chronic kidney disease or alpha klotho in the context of idiopathic pulmonary fibrosis, FGF23 can exert a protective effect." (PMID 37763754, 2023). "Furthermore, abnormally high expression of FGF23 in patients with chronic renal failure accelerates a series of extrarenal damages such as organismal calciphylaxis, atherosclerosis, secondary bone disease, and cognitive impairment of the nervous system." (PMID 36649363, 2023).